FANCA (FA complementation group A)
Description:
DNA repair protein that may operate in a postreplication repair or a cell cycle checkpoint function. May be involved in interstrand DNA cross-link repair and in the maintenance of normal chromosome stability.
Synonyms: FAA; FACA; FANCH; FA-H; FAH; FA; FA1
Tractability: PROTAC: ubiquitination databases record sites on it.
Gene: Protein-coding gene on chromosome 16 (89,726,683 to 89,816,977, reverse strand). Ensembl gene ENSG00000187741.
Subcellular location: Nucleus; Cytoplasm
Subcellular location (Human Protein Atlas): Nucleoplasm
Pathways (Reactome):
DNA Repair: Fanconi Anemia Pathway
Immune System: PKR-mediated signaling
Gene Ontology:
Molecular function: protein binding
Biological process: DNA repair; interstrand cross-link repair; protein-containing complex assembly; regulation of regulatory T cell differentiation
Cellular component: chromatin; Fanconi anaemia nuclear complex; nucleoplasm; nucleus; cytoplasm; cytosol
Genetic constraint (gnomAD): Loss-of-function variants: 219 observed, 182.22 expected, observed/expected ratio (o/e) 1.2, 90% interval 1.08 to 1.34. The synonymous counts are far from expectation, so gnomAD's model fits this gene poorly and the ratio says little. Missense variants: 2,530 observed, 1,782.2 expected, observed/expected ratio (o/e) 1.42, 90% interval 1.37 to 1.47. Synonymous variants: 987 observed, 708.93 expected, observed/expected ratio (o/e) 1.39, 90% interval 1.32 to 1.47.
Gene-disease validity (ClinGen):
ClinGen rates the evidence that FANCA causes each of these diseases.
Fanconi anemia complementation group A (autosomal recessive): Definitive.
Homologues: Orthologues: chimpanzee FANCA (98% identical), macaque FANCA (93% identical), dog FANCA (70% identical), rat Fanca (66% identical), mouse Fanca (66% identical), pig FANCA (66% identical), guinea pig FANCA (64% identical), rabbit FANCA (59% identical), tropical clawed frog fanca (40% identical), zebrafish fanca (25% identical).
Diseases named in the same sentence as FANCA in open-access papers:
FANCA is named in the same sentence as 142 diseases in open-access papers, as found by Europe PMC text mining. Sharing a sentence is not in itself a finding about the gene and the disease. The quoted sentences say what the papers report.
Fanconi anemia (154 papers, 2005 to 2026). Fanconi anemia (FA) is a hereditary DNA repair disorder characterized by progressive pancytopenia with bone marrow failure, variable congenital malformations and predisposition to develop hematological or solid tumors. "Of the 19 patients diagnosed with Fanconi anemia, the majority of mutations were found in the FANCA gene (n = 12), followed by FANCG (n = 4) and FANCC (n = 3)." (PMID 41520327, 2026). "FANCA is a tumor suppressor gene that encodes the protein Fanconi anemia complementation group A, which is a member of the Fanconi anemia core complex that assembles at damaged chromatin and activates the DNA response by coordinating BRCA 1/2 proteins." (PMID 41528596, 2026). "In this study, Fanconi anemia was genetically confirmed in 19 individuals, with the majority of pathogenic or likely pathogenic variants identified in the FANCA, FANCG, and FANCC genes." (PMID 41520327, 2026). "Mutations of FANCA are the most prevalent, making up 65% of the heritable Fanconi’s anemia cases that are a cancer predisposition syndrome with elevated risk for a variety of malignant neoplasms." (PMID 41528596, 2026). "Southern Indian castes: FANCA mutations (Fanconi anemia) were recurrent in Vysya communities because of founder effects." (PMID 40898550, 2025). "Fanconi anemia (FA) is a rare genetic disease characterized by loss-of-function variants in any of the 22 previously identified genes (FANCA–FANCW) that encode proteins participating in the repair of DNA interstrand crosslinks (ICLs)." (PMID 40244696, 2025). "Mutations in the Fanconi anemia (FA) pathway were present in 33.3% of patients, predominantly involving FANCA, FANCI, and FANCG." (PMID 40805139, 2025). "The diagnosis of Fanconi anemia was confirmed by FANCA gene mutation in 10 patients and FANCD2 mutation in one." (PMID 39941721, 2025). "FANCA is a tumor suppressor and DNA repair protein with germline mutations of FANCA associated with the cancer predisposition syndrome Fanconi Anemia." (PMID 39844043, 2025). "FANCA is the most frequently mutated gene in Fanconi Anemia, encoding a protein that forms part of the FA core complex responsible for mediating FANCD2 ubiquitylation during ICL repair." (PMID 40630542, 2025). "It is known that SDHD mutation is more often associated with head and neck paragangliomas, and FANCA mutation is associated with Fanconi anaemia." (PMID 39673085, 2024). "Mutations in the Fanconi anemia complementation group A (FANCA) gene are the most common cause of Fanconi anemia." (PMID 39717482, 2024). "Biallelic mutations in the FANCA gene, either in a compound heterozygous or homozygous form, are a cause of Fanconi anemia (#227650), which is characterized by chromosomal instability, bone marrow failure, and increased susceptibility to cancer." (PMID 37623222, 2023). "Loss-of-function mutations in FANCA cause Fanconi anemia, a genetic disorder characterized by bone marrow failure and a predisposition to cancer." (PMID 37821946, 2023). "FA18JTO hTERT cells, derived from a patient with Fanconi anemia and immortalized with stable hTERT expression, contained compound heterozygous mutations in the FANCA gene (c.1811delT and c.2546delC) that disrupted full-length FANCA protein expression." (PMID 37714828, 2023). "Otherwise, in FANCA-mutated Fanconi anemia characterized by pancytopenia and chromosomal instability due to dysregulated DNA repair, Notch1 overexpression facilitated defective hematopoietic cell proliferation." (PMID 36497257, 2022). "Another interesting finding in our cohort is the high incidence of monoallelic variants in other Fanconi anemia (FA) genes: FANCA, FANCC, FANCD2, RAD51C, FANCG and FANCI." (PMID 36290365, 2022). "The most widely mutated gene in fanconi anemia (FA) known as FANCA is a member of the FA core complex that recognizes interchain cross-linking and induces subsequent DNA repair." (PMID 35042833, 2022).
Fanconi anemia (continued). "Three consecutive strongly associated SNPs were also identified and located in FANCA, which is widely involved in the Fanconi anemia pathway." (PMID 35739846, 2022). "The bi-allelic variants in FANCA contribute to a large proportion of Fanconi anemia, an autosomal recessive disease characterized by progressive bone marrow failure." (PMID 35366911, 2022). "Here, we report that GR-CDXL1 displays a somatic biallelic mutation in BRCA2 and promoter deletion of Fanconi anemia pathway gene FANCA." (PMID 35511434, 2022). "Through trio-WES, two mutations were identified in the CDS of FANCA, a causal gene for Fanconi anemia of complementation group A (FANCA, OMIM#227650)." (PMID 36385762, 2022). "A promising approach for gene therapy of Fanconi Anemia (FA) is the generation of compensatory mutations in the mutated FANCA gene with the CRISPR-Cas9 technology in order to restore its functions." (PMID 36553489, 2022). "We detected germline variants in genes associated with Fanconi anemia in eight patients with ccpRCC (FANCA, 6/18; FANCI, 3/18)." (PMID 34512202, 2021). "Germline mutation detection showed that nine variants associated with Fanconi anemia (VAFAs) pathway (FANCA, 6/18; FANCI, 3/18) were identified in 18 ccpRCC patients." (PMID 34512202, 2021). "The 104- and 106-HIO were generated from patient specific iPSC which were derived from keratinocytes (104-HIO) or fibroblasts (106-HIO) biopsies of Fanconi anemia patients carrying a mutation in the FANCA gene." (PMID 32085439, 2020). "By this means, we identified two large intragenic deletions in FANCL and FANCA, highlighting the importance of searching for this type of variant when analyzing FA genes in patients with Fanconi anemia." (PMID 32235514, 2020). "Rare missense variants were identified in FANCA (Fanconi anemia complementation group A): c.1772G > A (p.R591Q) and c.3887A > G (p.E1296G)." (PMID 31535215, 2019). "Most fanconi anemia patients harbour homozygous or double heterozygous mutations in the FANCA (60-65%), FANCC (10-15%), FANCG (~10%) or FANCD2 (3-6%) genes." (PMID 29400309, 2018). "We have already reported the FANCA variant c.190–256_283+1680del2040dupC as a founder mutation among Macedonian fanconi anemia patients of Gypsy-like ethnic origin." (PMID 29400309, 2018). "The FANCA gene encodes a protein that is involved in a cell process known as the Fanconi anemia (FA) pathway." (PMID 25953249, 2015). "FANCA is considered a component of the Fanconi anemia core complex (including FANCA, B, C, E, F, G, L, M and other Fanconi anemia associated proteins (FAAP))." (PMID 24170812, 2014). "FANCA (Fanconi anemia, complementation group A) - mutations in this gene represent the most common cause of Fanconi anemia." (PMID 25077705, 2014). "The FANCA gene was initially associated with Fanconi anaemia, which is a recessive genetic disease, characterised by high chromosome breakage and increased sensitivity to agents that cause DNA damage and repair defects in the DNA damage." (PMID 23483937, 2013). "D598N, R951W, R1055W, R1117G, and F1263Δ are selected from FANCA mutations that cause Fanconi anemia." (PMID 24349332, 2013). "This novel regulation of FEN1 by FANCA is impaired in pathogenic FANCA mutants thus making the novel interaction physiologically relevant to Fanconi anemia." (PMID 24349332, 2013). "Some other founder mutations are specific to an ethnic and religious group such as the c.890_893del mutation in FANCA gene that underlies Fanconi anemia specifically among the Tunisian Jews." (PMID 22908982, 2012). "The association between the Fanconi Anemia family of genes with HPV persistence is also consistent with our previous analyses that reported FANCA variants associated with HPV persistence." (PMID 20084279, 2010). "The FANCA gene is one of the genes in which mutations lead to Fanconi anaemia, a rare autosomal recessive disorder characterised by congenital abnormalities, bone marrow failure, and predisposition to malignancy." (PMID 15860134, 2005).
Fanconi anemia (continued). "FANCA is one of the causative genes of Fanconi anemia and is a component of the FANC core complex." (PMID 40974087, 2025). "Moreover, 14% of the patients included in this study harbored deleterious mutations in Fanconi anemia genes (FANCA, FANCD2, FANCF, FANCG FANCI and FANCL) and in WRN, which have been reported to interact with BRCA1." (PMID 38184614, 2024). "An FANCA mutation involved in the Fanconi anemia pathway might have partially contributed to PARPi resistance in this patient." (PMID 37173992, 2023). "However, MN-IH-HR efficiency exceeded 75% in FANCA-mutated cells compared to WT FANCA-expressing cells, suggesting that gene mutations in patients with Fanconi anemia can be corrected using NICER." (PMID 37714828, 2023). "FANCA gene on chromosome 16q24 is one of the associated genes of Fanconi anemia (FA)." (PMID 40625579, 2023). "Besides, two heterozygous mutations were also detected in FANCA gene, resulted in a mild form of Fanconi Anemia." (PMID 36385762, 2022). "Since homozygous or compound heterozygous mutations of FANCA gene resulted in the recessive Fanconi anemia of complementation group A (FANCA), this gene might be the unlying molecular factor for the anemia phenotype of the proband." (PMID 36385762, 2022). "One missense variant was associated with the FANCA (Fanconi anemia complementation group A) gene." (PMID 32054482, 2020). "NSC 617145 [1,1′-(2,2-Dimethyl-1,3-propanediyl)bis[3,4-dichloro-1H-pyrrole-2,5-dione] is reported to be a candidate for chemically inducing synthetic lethality in Fanconi Anemia-deficient tumors harboring autosomal recessive mutations in either the FA group A (FANCA) or group D (FANCD2) genes." (PMID 30200453, 2018). "Exome sequencing identified a homozygous pathogenic variant in FANCA, causing Fanconi anemia." (PMID 30089087, 2018). "To evaluate whether stimulation of FEN1 by FANCA is physiologically relevant to Fanconi anemia, we created 5 more FANCA point mutations and purified them to near homogeneity." (PMID 24349332, 2013). "A homozygous variant of FANCA was found in two brothers with SCOS and Fanconi anemia, and subsequently a further pathogenic heterozygous variant in another unrelated patient." (PMID 41488147, 2025). "While Fanconi Anemia-associated genes BRCA2, FANCA and PALB2 are known PCa GT candidates, FANCD2 outranked FANCA, with FANCG, ECCR4, FANCE and FANCI (in order of ranking) potential candidates." (PMID 41038821, 2025). "In the first case, our current short-read NGS clinical pipeline identified what appeared to be a single heterozygous FANCA deletion (exons 1–23), in a 6-year-old male with a clinical presentation consistent with Fanconi anemia." (PMID 40385982, 2025). "BRCA2 and FANCA are key genes of the Fanconi anemia pathway, and their expression was also significantly lower in V30 than in the control mice." (PMID 38646488, 2024). "The genes FANCM, FANCA and XRCC2 are also directly involved in the Fanconi anaemia pathway, as biallelic variants in these genes can cause Fanconi anaemia." (PMID 39257928, 2024). "The oncoretroviral MSCV vector has been used for ex vivo transfer of the Fanconi anemia complementation group A (FANCA) gene to treat Fanconi anemia (FA)." (PMID 36992407, 2023). "The 16q24.3 deletion (91 kb), contains the gene for Fanconi anemia, complementation group A (FANCA), and the gene Spire‐type Actin Nucleation Factor 2, SPIRE2." (PMID 36349425, 2023). "The FANCA (Fanconi anemia, complementation group A) gene is a gene that codes for Fanconi anemia complementation group member protein." (PMID 36833207, 2023).
Fanconi anemia (continued). "In CRC, significant associations of HR (BRCA1, BRCA2, BARD1, PALB2 and BRIP1) and Fanconi anaemia (FANCA, FANCC and FANCG) genes with TMB were identified." (PMID 37821580, 2023). "The monoallelic germline alterations in FANCA and FANCC reflect carrier status only; biallelic alterations in these genes are associated with the autosomal recessive condition of Fanconi anemia." (PMID 36611031, 2023). "Each of these four genes is mutated in a hereditary disease/syndrome, which are the hereditary breast and ovarian cancer syndrome (BRCA1), α-gammaglobulinemia (BTK), Fanconi anemia (FANCA), and spastic paraplegia 4 (SPAST)." (PMID 36075911, 2022). "BRCA1 and the Fanconi anemia (FA) pathway factors FANCA, FANCD2, and TOP1 have been reported to bind R-loop during DNA damage repair." (PMID 36428700, 2022). "Fanconi anemia complementation group A (FANCA), one of the homologous recombination repair pathway genes, is a susceptibility gene to breast cancer and OC." (PMID 35280757, 2022). "MC1R gene is involved in the neuroactive ligand-receptor interaction and melanogenesis pathways while the FANCA gene was observed in the Fanconi anemia pathway." (PMID 35747604, 2022). "FANCA (Fanconi anaemia complementation group A) is a protein that is involved in the Fanconi anaemia pathway that is activated when DNA replication is blocked due to DNA damage." (PMID 35883549, 2022). "The FANCA gene is important for the repair of double-stranded DNA breaks and is involved in the cellular process known as the Fanconi anemia pathway." (PMID 34071259, 2021). "Among other genes with a prevalence of PVs >1% were APC (1.12%), involved in hereditary colorectal cancer, the breast cancer genes PTEN and BRCA1 (1.61%, 1.06%), and FANCA (1.04%), involved in Fanconi anemia." (PMID 34255164, 2021). "Noteworthy, even the gene carrier status for pathogenic mutations in some Fanconi anemia genes (FANCD2, FANCA, FANCB, FANCC) has been associated with higher risk of bone marrow failure under replicative cell stress conditions, such as chemotherapy." (PMID 33995067, 2021). "Most detected variants affected the Fanconi anemia/DNA repair pathway (34%, ATM, FANCA, FANCI, MLH1, MSH6, POLE, RAD51C, RAD51D) followed by mutations altering the SWI/SNF (SWItch/sucrose non-fermentable) complex (22%, ARID1A and SMARCA4)." (PMID 34200508, 2021). "FANCA participates in the Fanconi anemia (FA) pathway, which is involved in DNA interstrand cross-link (ICL) damage repair and crucial for maintaining the integrity of the genome." (PMID 34917121, 2021). "However, given that the mode of transmission is autosomal recessive for most of the meiosis or DNA repair genes, especially for genes of the Fanconi Anemia pathway, it is still debated whether a causal link between heterozygous FANCA variants and POI may exist." (PMID 33806855, 2021). "The Fanconi anemia pathway genes FANCB, POLN, DCLRE1A, UBA52, and FANCF genes were significantly (p < 0.01, T-test) downregulated after radiation only in FANCA-deficient HIO lines." (PMID 32085439, 2020). "The Fanconi anemia complementation group A (FANCA) gene is located at the telomere of chromosome 16 and is mutated in two-thirds of all Fanconi anemia (FA) cases due to the abundance of Alu elements." (PMID 33585230, 2020). "FANCA belongs to the Fanconi anemia complementation group (FANC) family and is known as one of the genes responsible for Fanconi anemia." (PMID 31931827, 2020). "In mammals, the main mechanism for ICL repair is the so-called Fanconi anemia (FA) pathway that involves 22 FANC (Fanconi anemia complementation group) genes (FANCA/ B/ C/ D1/ D2/ E/ F/ G/ I/ J/ L/ M/ N/ O/ P/ Q/ R/ S/ T/ U/ V and W)." (PMID 31484324, 2019).